PPP2R5E (protein phosphatase 2 regulatory subunit B'epsilon)
Description:
The B regulatory subunit might modulate substrate selectivity and catalytic activity, and might also direct the localization of the catalytic enzyme to a particular subcellular compartment.
Synonyms: B56E; B56epsilon
Tractability: PROTAC: ubiquitination databases record sites on it; its protein half-life has been measured.
Gene: Protein-coding gene on chromosome 14 (63,371,364 to 63,543,410, reverse strand). Ensembl gene ENSG00000154001.
Subcellular location: Cytoplasm
Subcellular location (Human Protein Atlas): Cytosol; Mid piece; Principal piece
Pathways (Reactome):
Disease: APC truncation mutants have impaired AXIN binding; AXIN missense mutants destabilize the destruction complex; CTNNB1 S33 mutants aren't phosphorylated; CTNNB1 S37 mutants aren't phosphorylated; CTNNB1 S45 mutants aren't phosphorylated; CTNNB1 T41 mutants aren't phosphorylated; Signaling by GSK3beta mutants; Truncations of AMER1 destabilize the destruction complex
Signal Transduction: Beta-catenin phosphorylation cascade; Degradation of beta-catenin by the destruction complex; Disassembly of the destruction complex and recruitment of AXIN to the membrane; Negative regulation of MAPK pathway; PI5P, PP2A and IER3 Regulate PI3K/AKT Signaling; RAF activation; RHO GTPases Activate Formins
Cell Cycle: Amplification of signal from unattached kinetochores via a MAD2 inhibitory signal; EML4 and NUDC in mitotic spindle formation; Mitotic Prometaphase; Resolution of Sister Chromatid Cohesion; Separation of Sister Chromatids
Immune System: Co-inhibition by CTLA4; Co-stimulation by CD28
Hemostasis: Platelet sensitization by LDL
Gene Ontology:
Molecular function: protein binding; protein phosphatase activator activity; protein phosphatase regulator activity
Biological process: signal transduction
Cellular component: cytosol; protein phosphatase type 2A complex; cytoplasm; nucleus
Genetic constraint (gnomAD): Loss-of-function variants: 4 observed, 47.38 expected, observed/expected ratio (o/e) 0.0844, 90% interval 0.041 to 0.19. The upper end of that interval is the gene's LOEUF score, 0.19, which puts it in group 1 of 6, group 1 being the genes least tolerant of losing a copy. Missense variants: 223 observed, 480.86 expected, observed/expected ratio (o/e) 0.46, 90% interval 0.41 to 0.52. Synonymous variants: 151 observed, 163.58 expected, observed/expected ratio (o/e) 0.92, 90% interval 0.81 to 1.06.
Homologues: Orthologues: rabbit PPP2R5E (100% identical), mouse Ppp2r5e (99% identical), pig PPP2R5E (99% identical), guinea pig PPP2R5E (99% identical), rat Ppp2r5e (99% identical), tropical clawed frog ppp2r5e (99% identical), dog PPP2R5E (98% identical), macaque PPP2R5E (95% identical), zebrafish ppp2r5eb (95% identical), chimpanzee PPP2R5E (88% identical), Drosophila melanogaster wdb (74% identical), Caenorhabditis elegans pptr-1 (66% identical), and 1 more. Paralogues in human: PPP2R5A (78% identical), PPP2R5B (71% identical), PPP2R5C (69% identical), PPP2R5D (67% identical).
Diseases named in the same sentence as PPP2R5E in open-access papers:
PPP2R5E is named in the same sentence as 24 diseases in open-access papers, as found by Europe PMC text mining. Sharing a sentence is not in itself a finding about the gene and the disease. The quoted sentences say what the papers report.
acute myeloid leukemia (2 papers, 2015 to 2019). Acute myeloid leukemia (AML) is a group of neoplasms arising from precursor cells committed to the myeloid cell-line differentiation. "HMGN2 is an anti-tumor effector molecule of CD8+T cells, FOXO3 is a core tumor suppressor in breast cancer; downregulation of PPP2R5E is a common event in acute myeloid leukemia." (PMID 31540229, 2019). "PPP2R5E, involved in apoptosis control, was proposed as TSG in acute myeloid leukemia." (PMID 26046463, 2015).
breast carcinoma (2 papers, 2019 to 2023). "The roles of PDPK1, PKN2, PPP2R2A, and PPP2R5E in PI3K pathway regulation of HER2+ breast cancer progression and inhibition by PGB-0-ol remain unclear." (PMID 38028209, 2023).
cognitive disorder (2 papers, 2021 to 2026). A disease affects cognitive processes. "Of the top 10 most significant proteins, six (PLOD1, MFN2, NGFR, PPP2R5E, C4A/C4B, and ITGAV) have previously been linked to AD and/or cognitive function, underscoring their potential as biomarkers of cognitive impairment." (PMID 42253369, 2026). "PPP2R5E is a PP2A regulatory subunit, and its deregulation has been reported to have important implications in both human cancer and cognitive disorders such as Alzheimer disease." (PMID 33810186, 2021).
colorectal cancer (2 papers, 2023). A primary or metastatic malignant neoplasm that affects the colon or rectum. "Published results indicate that PPP2R5E, PES1, RRM2B, GLRX, and CRKL are important in the prognosis and development of colorectal cancer." (PMID 37895091, 2023).
lung carcinoma (2 papers, 2013 to 2018). "In conclusion, our data suggested that the two functional SNPs (rs11453459->G of PPP2R1A and rs1255722A >G of PPP2R5E) are associated with risk of lung cancer in Chinese." (PMID 24204789, 2013).
Autoimmunity (1 paper, 2018). The occurrence of an immune reaction against the organism's own cells or tissues. "Similarly, the downregulated expression of PPP2R5E genes, exhibit the overexpression of regulatory T cells, ensuing the risk of autoimmunity." (PMID 29503661, 2018).
bladder cancer (1 paper, 2018). "We further evaluated the expression of DIAPH3, LMAN1, PPP2R5E, and UHMK1 in bladder cancer cell lines upon LINC00857 knockdown." (PMID 29856124, 2018).
chronic myelogenous leukemia (1 paper, 2023). "PPP2R5E encodes the serine/threonine protein phosphatase-2A regulatory subunit epsilon isoform involved in the PI3K/Akt, MAPK, and Ras signaling pathways and in the regulation of cancers, including chronic myelogenous leukemia." (PMID 38028209, 2023).
COVID-19 (1 paper, 2024). A disease caused by infection with severe acute respiratory syndrome coronavirus 2. "We subsequently identified two groups of specific DEPs: PPP2R5E, SGK3, CDC37, TSC2, and 20 other DEPs that were upregulated- or downregulated solely in the COVID-19 group, with no observed differences in the PQ group." (PMID 39301288, 2024).
dementia (1 paper, 2018). Loss of intellectual abilities interfering with an individual's social and occupational functions. "Interestingly, apolipoprotein E ε4 (APOE ε4), which is a genetic risk factor for AD and dementia with Lewy bodies, can cause PP2A inactivation by downregulating the expression of PPP2R5E, a regulatory subunit of the PPP2R5 subfamily." (PMID 29950985, 2018).
dengue (1 paper, 2018). "For dengue fever (DF), we found evidence of significant association with CHST10, AHRR, PPP2R5E and GRIP1 genes, which participate in the xenobiotic metabolism signaling pathway." (PMID 29447178, 2018). "The association of the four genes (CHST10, AHRR, PPP2R5E and GRIP1) from the xenobiotic metabolism signaling pathway with Thai DF patients is the first genetic evidence for its implication in dengue pathogenesis, although functional studies have already indicated this association before." (PMID 29447178, 2018).
melanoma (1 paper, 2022). A malignant, usually aggressive tumor composed of atypical, neoplastic melanocytes. "The PPP2R5E gene found on BTA10 in the study has role in the PI3K-Akt signalling pathway that regulates the MAPK in B16F10 mouse melanoma cells." (PMID 35747604, 2022).
non-small cell lung carcinoma (1 paper, 2022). A group of at least three distinct histological types of lung cancer, including non-small cell squamous cell carcinoma, adenocarcinoma, and large cell carcinoma. "Likewise, our group previously showed that miR-19b contributes to EGFR activation in non-small cell lung cancer (NSCLC) by targeting PPP2R5E." (PMID 36358647, 2022).
soft tissue sarcoma (1 paper, 2012). A malignant neoplasm arising from muscle tissue, adipose tissue, blood vessels, fibrous tissue, or other supportive tissues excluding the bones. "With regard to the B subunits of PP2A (PP2A-Bs), a recent study demonstrated that a SNP in PPP2R5E (the gene coding for B56ε, a B56 family regulatory subunit of PP2A) is associated with human soft tissue sarcoma." (PMID 22539979, 2012).
T-cell acute lymphoblastic leukemia (1 paper, 2023). Acute lymphoblastic leukemia of T-cell origin. "In fact, miR-19b negatively regulates PRKAA1 and BIM in T-cell acute lymphoblastic leukemia, in addition to PPP2R5E, resulting in an overall PI3K signaling pathway activation." (PMID 37175484, 2023).
tumor (7 papers, 2017 to 2023). "Additionally, MYBL2 can be dephosphorylated by activated PPP2R5E(B56ε)/iHAP1 complexes, causing tumor cells to enter an irreversible prometaphase." (PMID 36814821, 2023). "To test whether miR-19b was a post-transcriptional regulator of PPP2R5E in our tumor cells, we performed a luciferase assay." (PMID 37175484, 2023). "Thus, administering antagomiRs to block enhanced levels of miR-19b may be an interesting alternative therapeutic option as it specifically restores PPP2R5E expression in the tumour tissue." (PMID 29455644, 2018). "We highlighted the biological relevance of miR-19b as a direct negative regulator of PPP2R5E expression in CRC cells that promotes uncontrolled cell viability, migration, and colonosphere formation, which significantly contribute to tumor progression." (PMID 37175484, 2023). "Our analysis identified several candidate genes, including EXOC5, PPP2R5E, and SOS2, and showed that PPP2R5E and SOS2 expression levels correlated with MuD level in tumor cells to some extent." (PMID 31616474, 2019). "Furthermore, we evaluated the importance of PPP2R5E in the modulation of additional biological properties regulated by miR-19b in CRC cells, and the contribution of miR-19b/PPP2R5E axis in tumor progression through the regulation of different cellular processes." (PMID 37175484, 2023). "Moreover, miR-19b determines 5-FU resistance and predicts tumor progression in LARC, but the potential role of PPP2R5E in this issue was not investigated." (PMID 37175484, 2023).
cancer (6 papers, 2017 to 2023). A tumor composed of atypical neoplastic, often pleomorphic cells that invade other tissues. "After demonstrating the direct miR-19b regulation of PPP2R5E, we tested the relevance of the miR-19b/PPP2R5E axis modulating cancer cell viability." (PMID 37175484, 2023). "Of interest, PPP2R5E has been recently reported as a novel molecular target of allosteric PP2A activators with promising therapeutic implications in human cancer." (PMID 33810186, 2021). "In contrast, PPP2R2A was the most deleted gene found in > 20% of samples across 17 cancers, followed by the deletion of SLC2A4 in 16 cancers and five additional genes (FOXO3, PPP2CB, PPP2R2D, PPP2R5C and PPP2R5E) in 15 cancer types." (PMID 32807122, 2020).
infection (1 paper, 2010). The state of being infected such as from the introduction of a foreign agent such as serum, vaccine, antigenic substance or organism. "siRNAs that target PPP2R1B and/or PPP2R5E in Jurkat cells after Ad-TatSF2 infection caused a statistically significant decrease in apoptosis." (PMID 20862322, 2010). "mRNA levels of PPP2R1B and PPP2R5E were reduced by the PPP2R1B and PPP2R5E-specific siRNAs, respectively, but not by the control siRNA 24 hrs after infection." (PMID 20862322, 2010).
PPP2R5E also shares sentences with these, for which no sentence is quoted: Alzheimer disease (1 paper); cervical cancer (1); gastric cancer (1); Insulin resistance (1); renal cell carcinoma (1); respiratory disorders (1).